MPO (myeloperoxidase)
Diseases named in the same sentence as MPO in open-access papers (continued):
Sharing a sentence is not in itself a finding about the gene and the disease.
Autoimmunity (55 papers, 2011 to 2026). The occurrence of an immune reaction against the organism's own cells or tissues. "IIF showed limited sensitivity for PR3-associated autoimmunity, whereas MPO positivity correlated more strongly with IIF patterns and formalin resistance." (PMID 41975708, 2026). "The experimental anti-MPO GN murine model is particularly valuable as it enables the study of loss of tolerance and the development of active autoimmunity." (PMID 41256853, 2025). "The development of autoimmunity to the neutrophil protein myeloperoxidase (MPO) involves loss of tolerance to this self-antigen with activation of the innate immune system, production of MPO-ANCAs and the proliferation of effector anti-MPO CD4+ T cells." (PMID 36674855, 2023). "MPO-AAV is caused by autoimmunity to MPO, an abundant protein found inside our most common immune cell, neutrophil." (PMID 34394071, 2021). "It is caused by autoimmunity against neutrophil proteins, mainly myeloperoxidase (MPO) and proteinase-3 (PR3)." (PMID 34394071, 2021). "Given the induction of autoimmunity in this model, it can be used to interrogate mechanisms of loss of tolerance to MPO." (PMID 32373109, 2020). "In our degranulation assay, priming with C5a instead of TNF-α resulted in a 10-fold increased release of the ANCA antigens PR3 and MPO, implying an increased exposure and thereby possibly an increased risk of autoimmunity in C5a-driven inflammation." (PMID 31216309, 2019). "MPO facilitates the transformation of nuclear chromatin into a non-replicative and non-encoding state that occupies the extracellular space to participate in fighting infection and promoting coagulation but also contributing to cancer and autoimmunity." (PMID 40963017, 2025). "However, as both these models study acute injury, they do not assess the effects of DNase I over the longer term development and progression of anti-MPO autoimmunity and ANCA-associated GN." (PMID 40632882, 2025). "Notably, prolonged PTT associated with Anti-MPO (F = 4.492, P = 0.039), indicating potential coagulation-autoimmunity interactions." (PMID 41239211, 2025). "The authors suggest that MPO as a neutrophil intracellular protein indicates that repeated neutrophil destruction caused by altered autoimmunity could be involved in the pathogenesis of SS." (PMID 37569455, 2023). "The second implication, is that the extracellular NET MPO that is deposited is biologically active and may cause direct injury to the surrounding tissues and also become available as an autoantigen in autoimmunity in AAV." (PMID 33790907, 2021). "Thus, whilst the C3aR modulates some elements of disease pathogenesis, overall it is not critical in effector responses and glomerular injury caused by autoimmunity to MPO." (PMID 29315316, 2018). "Therefore, in experimental lupus nephritis, MPO-mediated suppression of pathogenic T cell autoimmunity overrides the local damaging effects of MPO in the kidney." (PMID 26904693, 2016). "DNase I inhibition of DC activation and lymph node migration supports the view that DNA (in adjuvants or recruited neutrophils) is a potent inducer of MPO autoimmunity." (PMID 40632882, 2025). "Anti-neutrophil cytoplasmic antibody (ANCA)-associated vasculitis (AAV) is a systemic autoimmune condition characterised by inflammation of small vessels, primarily driven by ANCAs targeting proteinase 3 (PR3) or myeloperoxidase (MPO)." (PMID 41222744, 2025). "The immunopathogenesis of MPO autoimmunity is biphasic, with an initial transient Th17 dominance followed by a sustained Th1 response, posing challenges for effective cytokine blockade." (PMID 40735321, 2025). "The activation of TLR2 stimulates IL-17A production, promoting Th17 cells activity, while TLR9 enhances anti-MPO driven autoimmunity through Th1 committed lineage pathway." (PMID 41256853, 2025).
Autoimmunity (continued). "While the mechanisms of DNase I clearance of ecDNA are well understood, the mechanisms by which this ecDNA clearance attenuates anti-MPO autoimmunity and GN is unclear." (PMID 40632882, 2025). "Our findings unveil a mechanism of drug-induced autoimmunity wherein stepwise chemical modifications of MPO lead to conformational changes and hydrazone adduct formation, producing a neoantigen that generates pathogenic autoantibodies." (PMID 40020049, 2025). "To evaluate anti-cytokine therapy at distinct disease phases, we induced anti-MPO autoimmunity in mice through MPO immunization and triggered GN using anti-glomerular basement membrane (GBM) globulin at early (day 20) and late (days 32 and 38) stages." (PMID 40735321, 2025). "Having established that DNase I is therapeutic even after establishment of anti-MPO autoimmunity in the 20-day cell-mediated model of anti-MPO GN, we next dissected mechanisms by which DNase I reduces systemic autoimmune responses to MPO." (PMID 40632882, 2025). "MPO-pulsed DCs stimulated with the TLR9 ligand CpG (a component of DNA) stimulate Th1 responses and MPO autoimmunity and promote kidney injury in experimental anti-MPO GN." (PMID 40632882, 2025). "The current study strongly supports a role for ecDNA acting as a pro-inflammatory DAMP mediating injury and autoimmunity in MPO-ANCA GN." (PMID 40632882, 2025). "To investigate this phenomenon, we utilized a 10-day model free of complicating GN to dissect out the role of DNase I in preventing systemic autoimmunity to MPO." (PMID 40632882, 2025). "MPO regulates neutrophil trafficking, phagocytosis, formation of extracellular traps, and MPO-triggered autoimmunity." (PMID 39992598, 2025). "Glomerular injury in this model of active anti-MPO autoimmunity is mediated by cellular effectors, and OVA-immunized mice injected with anti-GBM globulin serve as negative controls." (PMID 40632882, 2025). "TLR9 ligation enhanced dendritic cell activation upregulating CD40 and CD80 expression, promoting systemic anti-MPO autoimmunity and T cell recall responses and exacerbating kidney injury." (PMID 36674855, 2023). "TLR9 stimulated MPO pulsed dendritic cells promote anti-MPO autoimmunity by driving Th1 and predominantly Th17 immune responses." (PMID 36674855, 2023). "Toll-like receptors (TLR) provide a potential link between infection and anti-myeloperoxidase (MPO) autoimmunity." (PMID 36674855, 2023). "In summary this study demonstrates that MPO pulsed dendritic cells activated ex vivo through TLR9 ligation promote anti-MPO autoimmunity when transferred to naïve mice." (PMID 36674855, 2023). "An improved understanding of the critical molecular events that lead to the generation of anti-MPO autoimmunity in MPO-AAV will facilitate identification of specific targets for therapeutic intervention." (PMID 36674855, 2023). "TLR9 has been demonstrated to be an important mediator of autoimmunity and glomerular inflammation in a murine model of MPO-AAV." (PMID 36674855, 2023). "Our study reflects the importance of both Th1 and Th17 responses in the pathogenesis of TLR9 mediated anti-MPO autoimmunity and consequent kidney injury." (PMID 36674855, 2023). "TLR9 ligation has been shown to promote anti-MPO autoimmunity and glomerular vasculitis in murine MPO-AAV." (PMID 36674855, 2023). "This review scrutinizes the multifaceted roles of MPO in immunity, focusing on neutrophil-mediated host defense, tissue damage, repair, and autoimmunity." (PMID 36421487, 2022). "These actions include MPO orchestration of neutrophil trafficking, activation, phagocytosis, lifespan, formation of extracellular traps, and MPO-triggered autoimmunity." (PMID 36421487, 2022). "Studies in Treg-depleted mice showed that the inhibitory effects of MPO/BAY DCs on anti-MPO autoimmunity were dependent on Tregs." (PMID 34394071, 2021).
Autoimmunity (continued). "We have shown that Tregs not only inhibit the generation of anti-MPO autoimmunity, but that they also suppress established responses of MPO-specific CD4 T cells, CD8 T cells and B cells." (PMID 34394071, 2021). "In one model, wildtype mice are immunized with MPO to induce active MPO-specific autoimmunity, including MPO-ANCA and MPO-specific T cells." (PMID 34394071, 2021). "MPO-AAV can be induced in mice by immunizing animals with MPO which results in the development of active anti-MPO autoimmunity, followed by neutrophil lodgment in glomeruli and deposition of the autoantigen for subsequent recognition by MPO-specific T cells." (PMID 34721059, 2021). "C5aR1 modulates development of autoimmunity to MPO, with C5ar1−/− mice relatively protected from T cell mediated disease, as dendritic cells lacking the C5aR1 are not able to fully activate anti-MPO T cells." (PMID 32373109, 2020). "While the exact type of regulatory cell varies with different strategies, the mechanism of action in each of these three studies is via the generation of MPO-specific T cells that regulate and suppress established anti-MPO autoimmunity." (PMID 32373109, 2020). "Here, we show that a Staphylococcus aureus peptide, homologous to an immunodominant MPO T-cell epitope (MPO409–428), can induce anti-MPO autoimmunity." (PMID 31358739, 2019). "As ANCA production is critical in the pathogenesis of AAV, we measured the development of anti-MPO humoral autoimmunity in this disease model." (PMID 29315316, 2018). "On the other hand, stimulation of DCs by NET-bound MPO can result in the generation of MPO-specific autoimmunity and subsequent development of AAV." (PMID 26904693, 2016). "In mice, it has been shown that lipopolysaccharide (LPS) aggravates anti-MPO antibody induced injury in a TLR4 dependent manner, and a recent study showed that TLR2 and TLR9 ligands can drive the development of anti-MPO autoimmunity as well." (PMID 21915309, 2011). "Exogenous DNase I attenuates the development of anti-MPO autoimmunity." (PMID 40632882, 2025). "This demonstrates, for the first time to our knowledge, that vec-DNase I may be used as a biological therapeutic to attenuate the development or perpetuation of anti-MPO autoimmunity." (PMID 40632882, 2025). "CD40−/− dendritic cells were generated; these cells were pulsed with MPO and stimulated with the TLR9 ligand and their ability to induce nephritogenic autoimmunity when transferred to naïve wild type mice was compared to TLR9 stimulated MPO pulsed WT dendritic cells." (PMID 36674855, 2023). "CD40 is a critical second signal for the induction of anti-MPO autoimmunity." (PMID 36674855, 2023). "Defining the molecular mechanisms of TLR9-induced anti-MPO autoimmunity and glomerular injury may identify critical therapeutic targets for patients with AAV." (PMID 36674855, 2023). "The current study does not explore the effect of p110δ deficiency on autoimmunity to MPO, and one would predict that it will inhibit this in addition to the antiinflammatory effects we have demonstrated." (PMID 35818684, 2023). "Having demonstrated enhanced anti-MPO autoimmunity after transfer of TLR9 stimulated MPO pulsed dendritic cells, we hypothesized that the enhanced immune responses would facilitate glomerular inflammation and injury." (PMID 36674855, 2023). "Our data showing lower anti-MPO IgM levels in PwCF infected with S. aureus could also indicate that autoimmunity to MPO might decrease with the higher proportion of PwCF being positive for S. aureus nowadays compared to years or decades ago." (PMID 37767091, 2023). "Furthermore, MPO deficiency was associated with increased glomerular accumulation of neutrophils and induction of CD4+ T cell autoimmunity in a model of lupus nephritis." (PMID 36421487, 2022).
Autoimmunity (continued). "Externalization of MPO, together with other well-known antigens, such as double-stranded DNA and histones, through aberrant NET formation or impaired NET degradation, has been implicated in triggering autoimmunity in susceptible individuals." (PMID 36421487, 2022). "In terms of MPO and S. aureus, a liaison with the autoimmune response could even be more direct, since a 19mer peptide found in some strains is homologous with an MPO peptide and thus was designated as inducer of autoimmunity against MPO." (PMID 34204207, 2021). "These MPO-presenting inhibitory DCs were then given to mice with established anti-MPO autoimmunity." (PMID 34394071, 2021). "In one such model, autoimmunity to MPO is induced in mice by immunization with human MPO which results in a humoral (MPO-ANCA) as well as a cellular immune response to autologous mouse MPO." (PMID 33815414, 2021). "TLR2 ligands directed Th17 anti-MPO autoimmunity while TLR9 ligands supported Th1 immunity." (PMID 32373109, 2020). "The current studies not only identify a mimotope peptide, pSJH101 6PGD391–410 that induces anti-MPO T and B-cell autoimmunity, they also highlight both the sensitivity of such mimicry, as very similar sequences to the mimic peptide were unable to induce cross-reactivity." (PMID 31358739, 2019). "To determine whether this 6PGD397–408 sequence induced autoimmunity to MPO, we immunized C57BL/6 mice with 6PGD391–410 (391YFKNIVTDYQEALRDVVATG410)." (PMID 31358739, 2019). "As hypothesized, mice immunized with Variant 3 of 6PGD391–410 did not develop disease, demonstrating the relative specificity of the JH1 pSJH101 6PGD391–410 sequence in nephritogenic anti-MPO autoimmunity." (PMID 31358739, 2019). "Eventually, cross-reactivity between TPO and MPO may be another mechanism involved in the development of autoimmunity, due to the strong homology between amino acids 586–601 of TPO and amino acids 594–609 of MPO." (PMID 28626447, 2017). "Collectively, these data strongly indicate that rhDNase I inhibits the development of anti-MPO autoimmunity by reducing the frequency of Th1 MPO-specific effector cells while increasing the frequency of MPO-specific Tregs with increased capacity to respond to MPO." (PMID 40632882, 2025). "A common pathogenic sequence in MPO-ANCA ILD could be envisaged, involving genetic and environmental factors leading to lung damage through neutrophilic inflammation, subsequent autoimmunity, and fibrosis." (PMID 38445024, 2024). "To confirm the increased MPO autoimmunity and resultant kidney injury was TLR9 specific and reproducible, we utilized mice deficient in TLR9 (Tlr9−/−) to generate Tlr9−/− dendritic cells and compare to TLR9 stimulated MPO pulsed TLR9 intact C57BL/6 WT dendritic cells." (PMID 36674855, 2023). "Considering the ROC analysis results of serum MPO‐ANCA, higher diagnostic sensitivity and specificity of serum PR3‐ANCA may be due to the stronger stimulation of the infectious antigen by proteinase‐3‐related autoimmunity." (PMID 37872840, 2023). "Consequently, we speculated that the decrease in TEM17 cells accompanied by increases in TEM1 and TEM17.1 cells in the peripheral blood of patients with active MPO-AAV in our study were due to dynamic development of anti-MPO autoimmunity." (PMID 34289887, 2021). "DNase I is able to reduce autoimmunity to MPO with a reduced number of MPO specific lymphocytes (IL17a and IFNγ) in the draining lymph nodes and an increase in the number of MPO specific T regulatory cells, suggesting that DNase I may have an immunomodulatory role." (PMID 33790907, 2021). "Using our anti-MPO GN model where disease is mediated by active autoimmunity to MPO, we gave a single dose of vec-DNase I or vec-GFP 10 days after the establishment of anti-MPO autoimmunity." (PMID 40632882, 2025). "In addition, MPO or MPO-derived oxidants may function as signaling molecules to modulate neutrophil trafficking, activation and lifespan, and may trigger autoimmunity." (PMID 38189129, 2024).
Autoimmunity (continued). "This confirms TLR9 mediated dendritic cell activation as a mechanism of anti-MPO autoimmunity in AAV and further defines the link between infection and the generation of MPO specific autoimmune inflammation." (PMID 36674855, 2023). "Myeloperoxidase (MPO) is one of the most abundant NET proteins in which its enzyme, which is present in neutrophil phagosomes, plays an important role in autoimmunity and inflammation." (PMID 31766160, 2019). "First, MPO-specific autoimmunity develops in secondary lymphoid organs, resulting in the emergence of autoreactive effector CD4 T cells and MPO-ANCA-producing B cells." (PMID 26904693, 2016). "MPO-ANCA triggers the production of IL-6, IL-17A and IL-23 and increases the activation of neutrophils, conditions that promote Th17-mediated autoimmunity." (PMID 25964886, 2015). "Even though it is not well known, mechanism of PTU-induced AASV is explained as transforming of MPO (myeloperoxidase) into sulfonate by PTU which is highly antigenic and induces autoimmunity." (PMID 25506446, 2014). "In this model of MPO-ANCA GN, the effects of DNase I on ANCA-mediated injury can be assessed without any confounding effects of DNase I on anti-MPO autoimmunity, as the transfer of anti-MPO antibodies means that active T and B cell autoimmunity is absent." (PMID 40632882, 2025). "As expected OVA-immunized control mice did not develop anti-MPO autoimmunity as seen by the absence of GN and abnormal glomeruli and reduced leukocyte accumulation in the glomeruli." (PMID 40632882, 2025). "The enhanced MPO autoimmunity induced by TLR9 stimulated dendritic cells facilitates leukocyte recruitment into the glomerulus and histological and functional kidney injury akin to that seen in MPO-AAV." (PMID 36674855, 2023). "Serum PR3 (PR3-ANCA) or MPO (MPO-ANCA), often correlated with the primary syndromic AAV presentations, may be used clinically to demonstrate autoimmunity." (PMID 36552276, 2022). "To define the frequency of ANCA autoimmunity in patients with SARS-CoV-2 infection, we analyzed the serum ANCAs and the serum PR3 and MPO antigens by immunoassays in 124 adult patients with a diagnosis of SARS-CoV-2 infection (16 were asymptomatic and 108 were hospitalized) and 48 control subjects." (PMID 34578298, 2021). "Another common downside of these therapies, including past and currently-ongoing clinical trials in ANCA vasculitis, is that none of them specifically target anti-MPO autoimmunity to avoid complications due to their off-target, non-antigen-specific effects." (PMID 34394071, 2021). "In these models, autoimmunity to MPO is initiated in genetically intact mice, but the MPO-ANCA that develops is not sufficient in itself to induce disease." (PMID 32373109, 2020). "Glomerular injury in this model is not due to autoimmunity and autoreactivity to MPO is not present." (PMID 32373109, 2020). "In mice, autoimmunity to MPO induced by immunisation does not result in ANCA of sufficient pathogenicity to cause disease." (PMID 29315316, 2018). "Of note, the induction of autoimmunity by NET-activated DCs in the animal studies was not restricted to MPO but also resulted in the generation of anti-dsDNA antibodies which are associated with SLE." (PMID 26904693, 2016). "Further supporting evidence for a role for DNA activation in MPO-ANCA GN comes from the capacity for DNA subcomponents (e.g., CpG, bacterial DNA components) alone to provide sufficient adjuvant support to allow MPO immunization to induce anti-MPO autoimmunity and GN." (PMID 40632882, 2025). "We acknowledge that we have not excluded an effect of MPO inhibition on autoimmunity." (PMID 36154801, 2023). "These mice could develop anti-MPO autoimmunity but they could not develop GN unless neutrophils were infused into their circulation." (PMID 33790907, 2021). "However, study on the time kinetics and cellular effectors pattern of renal and systemic Th1 and Th17 immune responses in human anti-MPO autoimmunity is still lacking." (PMID 34289887, 2021).